PLAT (plasminogen activator, tissue type)
Diseases named in the same sentence as PLAT in open-access papers (continued):
Sharing a sentence is not in itself a finding about the gene and the disease.
lung carcinoma (12 papers, 2005 to 2025). "Survival data of lung cancer patients stratified by the expression of critical genes in the TCGA cohort were analyzed, and the PLAT was found to be a prognostic risk factor." (PMID 39754146, 2025). "Compared with those in PC9 lung cancer cells, the mRNA expression of PLAT, ITGB3, TNC, AKT, FAK and PI3K were upregulated in PC9GR." (PMID 39754146, 2025). "The overall survival of lung cancer patients with high PLAT expression is short by survival analyses." (PMID 39754146, 2025). "Systematic bioinformatics analysis confirmed the potential of PLAT as a biomarker in lung cancer and other cancers." (PMID 39754146, 2025). "Correlation analysis of genes coexpressed with PLAT in lung cancer was undertaken via Spearman correlation analysis, and 902 genes coexpressed with PLAT were screened according to |Cor|> 0.3, P < 0.05, and further combined with PLAT-related differential genes." (PMID 39754146, 2025). "The data obtained from the TCGA database revealed that the mRNA expression of PLAT in lung cancer tissues is significantly higher than in adjacent normal tissues." (PMID 39754146, 2025). "Previous studies revealed that high expression of PLAT would lead tumor growth, such as lung cancer and ovarian cancer." (PMID 38186223, 2024). "In this study, we demonstrate that VEGFA, ANGPT2, and PLAT are up-regulated in ADAM9-expressing lung cancer cells." (PMID 29118335, 2017). "Surprisingly, RET and PLAT were downregulated by 10- and 2.2-fold in RA-sensitive Calu-6 lung cancer cells, whereas both target genes were upregulated in both neuroblastoma cell lines." (PMID 16012519, 2005). "Furthermore, a significant correlation was observed between high expression of PLAT and higher M stage and pathological stage of lung cancer." (PMID 39754146, 2025). "The results indicate that ADI combined with gefitinib could synergistically inhibit the migration and invasion of gefitinib-resistant lung cancer cells by inhibiting PLAT." (PMID 39754146, 2025). "Compared with gefitinib administration alone, the difference was statistically significant after gefitinib combined with ADI, indicating that ADI combined with gefitinib could inhibit the migration and invasion of gefitinib-resistant lung cancer cells by interfering with PLAT expression." (PMID 39754146, 2025). "We show that ADAM9 promotes vascular remodeling in lung cancer cells by increasing the expression of VEGFA, ANGPT2, and PLAT." (PMID 29118335, 2017).
Arterial thrombosis (10 papers, 2011 to 2025). The formation of a blood clot inside an artery. "Currently, there are insufficient data to verify the association of mutations in the PLAT gene with venous or arterial thrombosis." (PMID 37808270, 2023).
venous thromboembolism (10 papers, 2015 to 2025). Occlusion of the lumen of a vein by a thrombus that has migrated from a distal site via the blood stream. "Pathogenetic mutations in PLAT associated with venous thromboembolism have rarely been reported." (PMID 37808270, 2023).
viral infection (9 papers, 2011 to 2024). "Another lncRNA (MLUGL00000087396), we found potentially transcribed as a part of two exons of the PLAT protein-coding gene and down-regulated (log2 fc = −1.67) during viral infection." (PMID 32289119, 2020). "Notably, the expression levels of PLAT were significantly upregulated upon viral infection in the mid‐aged mice ECs." (PMID 38098255, 2024).
type 2 diabetes (8 papers, 2012 to 2024). "PLAT mRNA levels were increased by 2.4-fold in islets from donors with type 2 diabetes compared with control islets." (PMID 39245780, 2024). "Importantly, we confirmed our findings in human islets, showing that PLAT expression is increased with type 2 diabetes." (PMID 39245780, 2024). "Finally, PLAT expression was increased in islets from donors with type 2 diabetes." (PMID 39245780, 2024). "Finally, PLAT expression was significantly increased by 2.4-fold in islets from donors with type 2 diabetes (n=4) vs islets from donors without type 2 diabetes (n=7) (p≤0.05)." (PMID 39245780, 2024). "Finally, to confirm the findings in human samples, PLAT expression was measured in freshly isolated islets from donors with and without type 2 diabetes." (PMID 39245780, 2024).
liver disease (7 papers, 2013 to 2025). "In addition, state #5 was identified as PDPN, FOXC2, and PROX2-expressing lymphatic-specific ECs; state #6 as a subpopulation expressing PLAT, whose protein level is increased in patients with liver disease; and, states #23, #32 and #34 as liver-specific liver sinusoidal ECs (LSECs)." (PMID 39748128, 2025).
lung fibrosis (7 papers, 2019 to 2025). "In keeping with a role of tPA in human lung fibrosis was the identification in a publicly available dataset that there is an increased expression of PLAT (tPA) by IPF epithelial cells." (PMID 30050057, 2019). "Although not shown in the setting of lung fibrosis, VPA was demonstrated to upregulate the expression of tissue plasminogen activator (t-PA/PLAT) in the vasculature of mice and men while downregulating PAI-1." (PMID 35626663, 2022).
neuroblastoma (7 papers, 2005 to 2025). Neuroblastoma (NB) is the most common solid, extracranial childhood tumor. "Retinoid treatment of MYCN transgenic mice bearing neuroblastoma altered the expression of five of nine target genes examined (RARβ2, CYP26A1, CRBP1, DUSP6, PLAT) in neuroblastoma tumour tissue in vivo." (PMID 16012519, 2005). "Although the levels of PLAT and GRN expression are inversely correlated with neuroblastoma patient survival, PLAT has a complex role in cancer progression." (PMID 38495925, 2024). "PTX3 and PLAT are critically involved in sEV-induced neuroblastoma metastasis, while GRN plays no significant role." (PMID 38495925, 2024).
Arthritis (6 papers, 2006 to 2025). Inflammation of a joint. "A putative protective role for PLAT in arthritis has also been shown in experimental models of RA." (PMID 16356191, 2006).
colon cancer (6 papers, 2011 to 2024). "In human, the increased expression of the plasminogen activator inhibitor was associated with the occurrence of distant metastasis in colon cancer, probably leading to decreased levels of PLAT which would corroborate our findings." (PMID 23739040, 2013).
glioblastoma (6 papers, 1989 to 2025). The most malignant astrocytic tumor (WHO grade IV). "Inhibition of PLAT may have a great effect on reducing glioblastoma cell invasion in preclinical studies." (PMID 39606019, 2024). "PIK3CG, SRC, AURKA, CDK7, and PLAT might be key molecular targets of plinabulin in glioblastoma." (PMID 39877641, 2025). "Furthermore, single-cell RNA sequencing (scRNA-seq) has provided crucial insights into the transcriptomic heterogeneity of glioblastomas, identifying key genes such as PDGFA, PDGFRA, CREB1, and PLAT that are strongly linked to tumor progression and patient survival." (PMID 40332008, 2025).
nasal polyps (6 papers, 2021 to 2025). "In nasal polyps, hypermethylation of the proximal promoter of the tissue-type plasminogen activator gene (PLAT) can lead to decreased PLAT expression due to negative regulation by Th2 cytokines, resulting in excessive fibrin deposition." (PMID 37176151, 2023). "The coagulation system dysregulation also plays a role in the tissue remodeling of nasal polyps with reduction of PLAT and upregulation of F13A1." (PMID 35095530, 2021).
schizophrenia (6 papers, 2015 to 2026). A major psychotic disorder characterized by abnormalities in the perception or expression of reality. "In a large sample of Japanese schizophrenia individuals, the association between the mental disorder and two single nucleotide polymorphisms of PLAT, the human tPA gene, rs2020922 and rs8178817, was highly significant." (PMID 26731441, 2016). "provided additional reasoning and evidence of a connection, finding lower PLAT levels among 70 schizophrenia patients compared with 98 age-matched controls." (PMID 29875399, 2018). "Since the principal regulator of PLAT levels is SERPINE1, Hoirisch-Clapauch and Nardi46 postulated that inflammatory conditions could increase the risk of schizophrenia through mechanisms involving SERPINE1 levels." (PMID 29875399, 2018).
heart failure (5 papers, 2020 to 2025). Inability of the heart to pump blood at an adequate rate to meet tissue metabolic requirements. "F2R, as the activated upstream regulator, upregulated PLAT, which was involved in heart failure and arrhythmia." (PMID 32423033, 2020).
asthma (4 papers, 2017 to 2024). "However, PLAT levels significantly decreased in patients with asthma." (PMID 38975344, 2024).
colorectal cancer (4 papers, 1989 to 2022). A primary or metastatic malignant neoplasm that affects the colon or rectum. "Given the importance of PLAT for ECM homeostasis, presumably the up-regulation of PLAT mRNA, which is associated with human pancreatic adenocarcinoma and colorectal cancer contributes to tumour metastasis." (PMID 19200380, 2009).
hepatocellular carcinoma (4 papers, 2015 to 2023). A malignant tumor that arises from hepatocytes. "A study of PLAT promoter methylation in human umbilical vein EC (HUVEC) and in primary human hepatocytes and hepatoma cells suggested that promoter methylation is associated with a low production of t-PA." (PMID 27973546, 2016).
Hydrocephalus (3 papers, 2016 to 2024). Hydrocephalus is an active distension of the ventricular system of the brain resulting from inadequate passage of CSF from its point of production within the cerebral ventricles to its point of absorption into the systemic circulation. "In summary, we describe a recessive disorder characterized by obstructive hydrocephalus, Dandy–Walker malformation and intellectual disability in individuals with loss-of-function variants in PLAT." (PMID 39574431, 2024). "All together, these observations further strengthen the association between loss of PLAT function and the development of obstructive hydrocephalus." (PMID 39574431, 2024). "Here, we describe homozygous truncating variants in the PLAT gene in four cases, from three consanguineous families, presenting with obstructive hydrocephalus and DWM." (PMID 39574431, 2024). "Interestingly, plasminogen deficiency has also been shown to cause obstructive hydrocephalus and Dandy–Walker malformation, suggesting that loss of PLAT causes these defects by disrupting plasmin production." (PMID 39574431, 2024). "In summary, we describe a disorder characterized by obstructive hydrocephalus, DWM and intellectual disability in individuals with loss-of-function variants in PLAT." (PMID 39574431, 2024). "It remains unclear whether the pathogenesis of DWM associated with the loss of PLAT and PLG involves the same mechanism underlying the development of hydrocephalus." (PMID 39574431, 2024).
non-small cell lung carcinoma (3 papers, 2021 to 2025). A group of at least three distinct histological types of lung cancer, including non-small cell squamous cell carcinoma, adenocarcinoma, and large cell carcinoma. "A previous study demonstrated its correlation with anti-apoptosis and tumor proliferation, findings that the knockdown of PLAT restored anticancer effect of gefitinib in non-small cell lung cancer (NSCLC)." (PMID 33919109, 2021). "Moreover, PLAT participated in proliferation, invasion and migration of non-small cell lung cancer as well as well as gefitinib resistance." (PMID 35155430, 2022).
thyroid cancer (3 papers, 2010 to 2024). "And when the exogenous human VEGFA (hVEGFA) was increased, the inhibition of PLAT was restrained, suggesting that PLAT inhibits thyroid cancer angiogenesis through VEGFa." (PMID 38186223, 2024). "To learn more about how PLAT affects thyroid cancer cells, we conducted cell scratch experiments in IHH4 cell lines." (PMID 38186223, 2024). "However, according to our findings, PLAT overexpression could inhibit the migratory capacity of thyroid cancer cells." (PMID 38186223, 2024). "Thus, we propose that PLAT may inhibit thyroid cancer cell proliferation and migration by suppressing the phosphorylation of VEGFR2 and further inhibiting the ERK signaling way." (PMID 38186223, 2024). "What’s more, PLAT in thyroid cancer cells can inhibit HUVEC proliferation and tube formation through VEGFa/VEGFR2, which is a new finding in thyroid cancer." (PMID 38186223, 2024).
chondrosarcoma (2 papers, 2012). A malignant cartilaginous matrix-producing mesenchymal neoplasm arising from the bone and soft tissue. "They found that the high-grade dedifferentiated components of the tumors—but not the low-grade components of the same tumors, nor conventional chondrosarcomas-exhibited robust, diffuse coexpression of PLAU and PLAT." (PMID 22448124, 2012).
Follicular Thyroid Cancer (2 papers, 2019 to 2024). "Rudzikaet al. found that PLAT was differently expressed in human follicular thyroid carcinoma (FTC) tissues compared with normal tissues, suggesting that PLAT plays an active role in vascularization." (PMID 38186223, 2024).
gastric ulcer (2 papers, 2018 to 2022). An ulcerated lesion in the mucosal surface of the stomach.
lung adenocarcinoma (2 papers, 2024 to 2025). A carcinoma that arises from the lung and is characterized by the presence of malignant glandular epithelial cells. "Aidi injection inhibits the migration and invasion of gefitinib-resistant lung adenocarcinoma cells by regulating the PLAT/FAK/AKT pathway." (PMID 39754146, 2025).
sarcoidosis (2 papers, 2021 to 2022). Sarcoidosis is a multisystemic disorder of unknown cause characterized by the formation of immune granulomas in involved organs. "Moreover, some proteins in Class 1, including IL17RA, growth differentiation factor 15, FK506-binding protein 10, and PLAT, are associated with sarcoidosis pathogenesis." (PMID 35178414, 2022). "SARS-CoV2 ORF8 host targets belonging to the sarcoidosis gene panel (IL17RA, EMC1, PLD3, GDF15, FKBP10, ADAM9, and PLAT) highlight significant pathways related to sarcoidosis pathogenesis." (PMID 34440765, 2021).
anaplastic oligodendroglioma (1 paper, 2016). A WHO grade III oligodendroglioma with focal or diffuse malignant morphologic features (prominent nuclear pleomorphism, mitoses, and increased cellularity). "Our gene signature also contained proneural genes, BMP2, DCX, IGFBP2, PDPN, and PLAT, which are associated with anaplastic oligodendroglioma harboring 1p/19q co-deletion." (PMID 27323413, 2016).
Atrophy (1 paper, 2011). Any weakening or degeneration, especially through lack of use. "Two highly up-regulated genes, SLC44A4 and PLAT, could be associated with the symptoms of vaginal dryness and atrophy." (PMID 22073175, 2011).
breast invasive carcinoma (1 paper, 2024). "Amplification was found to be the most prevalent alteration type for SERPINC1 and PLAT, with high amplification frequencies notably observed in UCS, liver hepatocellular carcinoma (LIHC), CHOL, and breast invasive carcinoma (BRCA)." (PMID 39179711, 2024).
cholangiocarcinoma (1 paper, 2024). A carcinoma that arises from the intrahepatic biliary tree (intrahepatic cholangiocarcinoma) or from the junction, or adjacent to the junction, of the right and left hepatic ducts (hilar cholangiocarcinoma). "Our radar plots revealed that F3, SERPINC1, F2, PLG, and PLAT exhibited the highest positive correlation with TMB in uterine carcinosarcoma (UCS), cholangiocarcinoma (CHOL), CHOL, thymoma (THYM) and LGG, respectively." (PMID 39179711, 2024).
myxoma (1 paper, 2024). A benign soft tissue neoplasm characterized by the presence of spindle and stellate cells, lobulated growth pattern, and myxoid stroma formation. "We found a myxoma subpopulation, primarily located at the terminal end of one myxoma differentiation trajectory, exhibits a high expression of PLAT, a gene associated with cell migration and tissue remodeling." (PMID 39090109, 2024).
peritoneal adhesions (1 paper, 2025). "Genetic variants within the PLAT gene or its regulatory regions may influence individual susceptibility to peritoneal adhesions." (PMID 40699873, 2025). "However, specific studies focusing on the role of the PLAT gene in peritoneal adhesions may be limited." (PMID 40699873, 2025).
pheochromocytoma (1 paper, 2022). "Using proteomics detection and analysis, it was found that the differential protein COX4I2 was significantly up-regulated in the pheochromocytoma samples of the rich blood supply group, while the differential protein in the poor blood supply group was PLAT." (PMID 36172142, 2022).
thyroid disease (1 paper, 2013). "We assessed the hematological profiles (WBCs, RBCs, HGB, and PLAT) in immunological thyroid disease patients." (PMID 23691348, 2013).
viral myocarditis (1 paper, 2021). Myocarditis that is caused by an infection with a viral agent. "Subsequently, we learned intermolecular interactions of herbal components and their targeting heart-tissue-specific CHRM2, FABP3, TNNC1, TNNI3, TNNT2, and SCN5A and cardiac-myocytes-specific IL6, MMP1, and PLAT coupled with viral myocarditis." (PMID 34456633, 2021).